ENSG00000279284 ( gene)
Diseases named in the same sentence as ENSG00000279284 in open-access papers (continued):
Sharing a sentence is not in itself a finding about the gene and the disease.
tumor (continued). "This protein seems to have dual functions in tumorigenesis, where it can act either as a tumor promoting gene or as a tumor suppressor gene." (PMID 24302991, 2013). "Recently, AHRR has been proposed to function as a putative new tumor suppressor gene based on some relevant studies in multiple types of human cancers." (PMID 22952704, 2012). "In summary, our data indicate that microRNA-126 is a tumor-suppressor gene in NSCLC and low microRNA-126 expression is a significantly unfavorable prognostic factor in NSCLC patients." (PMID 22900072, 2012). "For example, in epidermis, Notch1 is a tumour suppressor gene that represses the Wnt/β-catenin pathway, while Wnt signalling is known to promote epidermis neoplasia." (PMID 22615875, 2012). "Loss of PLAGL1 expression is frequently observed in many human tumours, consistent with its proposed role as a tumour-suppressor gene." (PMID 22723905, 2012). "AKAP12/Gravin (A kinase anchor protein 12) is one of the A-kinase scaffold proteins and a potential tumor suppressor gene in human primary cancers." (PMID 21918680, 2011). "Infact, the same microRNA can act as an oncogene in one biological condition and as a tumor suppressor gene in another." (PMID 19513126, 2009). "Globally, KLF4 and KLF6 are considered as tumor suppressor gene, whereas KLF5 promotes cell proliferation." (PMID 20119532, 2009). "Carcinoembryonic antigen-related cell adhesion molecule 1 (CEACAM1), a cell adhesion molecule expressed in a variety of cell types is a putative tumor suppressor gene." (PMID 18507857, 2008). "Merlin, the product of the Neurofibromatosis type 2 (NF2) tumor suppressor gene, belongs to the ezrin-radixin-moesin (ERM) subgroup of the protein 4.1 superfamily, which links cell surface glycoproteins to the actin cytoskeleton." (PMID 16324214, 2005). "We subjected the promoter regions of two genes residing at 11p, namely the tumour-suppressor gene WT1 (Wilms' tumour gene) (11p13) and the calcitonin gene (11p15.5), to methylation analysis in human sporadic colorectal cancer using genomic sequencing." (PMID 9365158, 1997). "SORBS2 is a tumor-suppressor gene predominantly expressed in myofibroblasts." (PMID 41766902, 2026). "Multiple studies reported that HIF1A may function as a tumor suppressor gene, whereas EPAS1 acts as an oncogene." (PMID 39477683, 2025). "The JCHAIN plays an important role in tumour immunity as an immune-related gene." (PMID 41010015, 2025). "SIRT5 exhibits dual functionalities: it can promote tumor proliferation, metastasis, drug resistance, and metabolic reprogramming, thereby acting as an oncogene; conversely, it can also inhibit tumor cell growth and induce apoptosis, functioning as a tumor suppressor gene." (PMID 39944690, 2025). "We found that low PLCG1 expression was associated with poor survival outcomes, which may function as a tumor suppressor gene in GBM." (PMID 40761791, 2025). "For instance, in particular cancer types, miR-155 acts as an oncogene; in others, it may serve as a tumor suppressor gene." (PMID 39963112, 2025). "In addition to regulating mitophagy, Ambra1 acts as a tumor suppressor gene in vivo; it inhibits cell cycle progression into the G1-S phase by promoting the degradation of cyclin D." (PMID 40141351, 2025). "PLIN1 is recognized as a tumor suppressing gene in multiple malignancies, such as HCC." (PMID 39870645, 2025). "The results of the miRNA microarray analysis suggest that DDX3 may function as an oncogene or a tumor suppressor gene by regulating the expression of a small subset of miRNAs." (PMID 39543456, 2025). "Moreover, miR-671-5p was identified as a tumor suppressor gene, inhibiting HCC cell migration, invasion, and EMT." (PMID 38166853, 2024). "Our objective was to investigate whether DEPDC1B functions as a tumor suppressor gene in COAD by influencing the immune microenvironment of tumors." (PMID 39087856, 2024).
tumor (continued). "Notably, DCDC2 has been identified as a candidate tumor suppressor gene in HCC through triple combination array analysis." (PMID 38658618, 2024). "In conclusion, our study highlights SMYD4 as a tumor suppressor gene across various solid tumors." (PMID 38892284, 2024). "In addition, DCA was significantly positively correlated with Lrmp (a tumor promotion gene), and TDCA was significantly positively correlated with Hnrnpa2b1." (PMID 38982226, 2024). "BCL2 is an apoptosis-inhibiting gene and is considered an influential factor in tumor cell production and proliferation, and it may play a role in the HF growth cycle and morphogenesis." (PMID 38674344, 2024). "PTEN is a tumor suppression gene that is commonly deleted at chromosome 10q23." (PMID 39156315, 2024). "Findings of recent years indicate that RIPK3 is a tumor suppressor gene." (PMID 38397165, 2024). "It was found to facilitate tumor cell apoptosis and may be a tumor suppressor gene through involving the JAK/STAT1 pathway." (PMID 39737399, 2024). "MiR-485-5p has been identified as a tumor suppressor gene in various cancers." (PMID 37348024, 2023). "The GSE14333 dataset was used as the validation cohort to further validate the hypothesis that ZNF880 may function as a possible tumor suppressor gene in CRC in this study." (PMID 37370088, 2023). "Therefore, our findings suggest that miR-375 acts as a tumor suppressor gene in GC, which is consistent with previous studies." (PMID 38505381, 2023). "PP2A is an important regulator of signal transduction pathways and is a tumor suppressor gene." (PMID 36975444, 2023). "ASXL1 plays a role in chromatin remodelling and is a tumor suppressor gene." (PMID 37379307, 2023). "This miR leads to the downregulation of FOXO3a (the Forkhead transcription factor O subfamily), which normally acts as a tumour suppressor gene, increases OSCC chemoresistance for DDP, and is directly associated with aggressive progression and poor prognosis in cancers." (PMID 37242569, 2023). "This in turn suggests that SEC23A itself might also act as a tumor-promoting gene, at least in STAD." (PMID 37046730, 2023). "Another gene downregulated by ~nine-fold in GEN-treated TM4 cells is Usp18 (Ubiquitin specific protease 18), shown to promote proliferation and be negatively regulated by Wt1 (Wilms tumor gene), a transcription factor that plays a role in spermatogenesis and in inhibiting interferon signaling." (PMID 37443838, 2023). "This could be explained by the fact that it acts as tumor suppressor gene and is consistent with the reported poor survival rates of reduced levels of microRNA-125a in different tumors." (PMID 36892621, 2023). "If the key target of the miRNA gene in a specific cell type is an oncogene, the miRNA gene can be considered a tumor suppressor gene; if the target of the miRNA gene is a tumor suppressor gene in different cell types, the miRNA gene can be considered an oncogene." (PMID 37371458, 2023). "As a tumor-suppressor gene, JWA plays an important role in blocking pan-tumor progression." (PMID 37240137, 2023). "PTPRM has an important role in tumorigenesis as a tumor suppressor gene." (PMID 37403117, 2023). "Besides lung, CCNDBP1 has been proposed to be a tumor suppressor gene for multiple tissues, including prostate, breast, liver, ovary, lymph, retina, colon, neuroglial, bone and lens epithelial cell through interacting with different proteins." (PMID 37058478, 2023). "Evidence shows that NCCRP1 plays an essential role in tumour development, and whether it acts as a tumour suppressor gene or oncogene depend upon tumour types." (PMID 38106991, 2023). "PRAME was found as a tumor-promoting gene in hematological system neoplasms." (PMID 36980687, 2023). "Similar to NCCRP1, USP19 is aberrantly expressed in multiple cancers and may act as a tumour suppressor gene or oncogene, which relies upon the tumour type." (PMID 38106991, 2023).
tumor (continued). "Moreover, increasing evidence has shown that PER2 acts as a tumor suppressor gene to inhibit the proliferation of tumor cells." (PMID 37069338, 2023). "Our findings indicate that KIAA1456 is a novel tumour suppressor gene and may be a possible therapeutic target in clinical practice." (PMID 37056382, 2023). "FOXO3 is commonly regarded as a tumor-suppressive gene in cancer." (PMID 34795388, 2022). "CHD5 has previously been reported to be a potential tumor suppressor gene in various solid tumors." (PMID 35955624, 2022). "In addition to its involvement in neuropsychiatric disorders, EGR1 has also been widely examined in the field of cancer where it plays paradoxical roles as a tumor suppressor gene or oncogene." (PMID 36338037, 2022). "In addition, as a potential tumor suppressor gene, C2orf40 inhibits the expression levels of cell cycle-related proteins (CCNE1 and CDK1), and blocks the cell cycle in G2/M phase." (PMID 35676661, 2022). "Indeed, in the context of neoplasm, E‐cadherin has long been proved as a tumor‐suppressor gene inhibiting cancer initiation and progression." (PMID 35601657, 2022). "It potentially suggested that miR-149 may play a role as a tumor suppressor gene in the Hp-induced pathological evolution of gastric mucosa." (PMID 36712871, 2022). "MiR-21-5p has been testified to be a tumor suppressor gene with decline in multiple cancers." (PMID 35191804, 2022). "RUNX1 is a member of the RUNX family of transcription factors (RUNX1, RUNX2 and RUNX3), and is known to influence the malignancy of many neoplasms, including leukaemia, and to act as an oncogene or tumour suppressor gene with diverse functions depending on the tumour." (PMID 36085167, 2022). "PTTG1 is a tumour transforming gene, which can cause cell transformation without the participation of any auxiliary gene, and is closely related to the occurrence of many tumours." (PMID 35037540, 2022). "Meg3 is a maternally expressed imprinted gene that functions as a lncRNA tumor suppressor." (PMID 35664469, 2022). "Together, these results suggest that NEDD4L acted as a tumor suppressor gene in LUAD." (PMID 35090513, 2022). "Until recently, researchers found LHPP function as a tumor suppressor gene in multiple cancers." (PMID 36484014, 2022). "CPNE1, a tumor-related gene, plays the role of proto-oncogene to promote tumor development." (PMID 35139863, 2022). "A substantial number of studies have reported that AURKB is a tumor-related gene." (PMID 35088239, 2022). "NRF2 was considered to have two sides to its roles, it may play as either an oncogene or a tumor suppressor gene based on different cellular environments." (PMID 35163707, 2022). "These contradictory reports suggest that FAM198B may play dual roles, i.e. as an oncogene role or as a tumor suppressor gene in different cancer contexts, possibly also indicating that FAM198B may have different effects in different cells." (PMID 35587159, 2022). "SMAD4 is a tumor-suppressor gene, acting as a downstream regulator of the TGF-β pathway." (PMID 35049691, 2022). "A recent study proposed that ZNF395 is a novel tumor suppressor gene." (PMID 36139015, 2022). "However, most reports demonstrated that this miRNA is a tumor suppressor gene with lower expression in diverse cancers." (PMID 35444696, 2022). "ACSL3 has a favorable correlation with CTNNB1, a recognized tumor-promoting gene." (PMID 36338658, 2022). "miR-323a-3p is located on chromosome 14q32.31 and acts as a tumor suppressor gene in CRC." (PMID 35096064, 2022). "PTEN, a tumor suppressive gene, was identified as a direct target gene of miR-4461 in OC cells." (PMID 33767986, 2021). "These previous findings suggested that Spred2 function as a potential tumor suppressor gene." (PMID 34818323, 2021). "The study reported that GADD45G might act as a tumor suppressor gene and upregulation inhibits cell proliferation." (PMID 34299042, 2021).
tumor (continued). "Interestingly, ATF3 can act as an oncogene or as a tumor suppressor gene, depending on the type of tumor and the cellular context." (PMID 33539340, 2021). "Some reports suggest that miR-137-3p acts as a tumor suppressor gene in cancer." (PMID 33968763, 2021). "Additionally, NFAT1 was also found to act as a tumor suppressor gene to block cell cycle progression by directly regulating cyclin E expression in B lymphocytes." (PMID 34257525, 2021). "S100A4 is a well-known tumor promoting gene and is the most studied one in HCC." (PMID 33815482, 2021). "Published data confirmed that miR-145 may be a tumor suppressor gene expressed in a variety of tumor tissues (including ovarian cancer, cervical cancer, breast cancer and colorectal cancer), and its expression level is significantly lower than normal tissues." (PMID 33407764, 2021). "We found that miR‐378a‐3p acted as a tumor‐suppressor gene in HCC." (PMID 33634974, 2021). "In other words, miR-375 plays a similar tumor suppressor gene." (PMID 32382558, 2020). "The lactoferrin (LTF) gene, located at 3p21.3, acts as a tumor suppressor gene in diverse tumors." (PMID 33585219, 2020). "Phosphatase and tensin homolog (PTEN) acts as a tumor suppressor gene." (PMID 32134893, 2020). "The studies confirmed the hypothesis that CLU could indeed act as a tumor suppressor gene by knockout of the CLU gene." (PMID 33299887, 2020). "The genetic data and the IHC analysis of ESCC samples indicated that ZNF750 might act as a tumor suppressor gene in ESCC." (PMID 32042337, 2020). "Altogether, our data support a role of BDH2 as a tumour-suppressor gene in NPC." (PMID 31819181, 2020). "We identified a tumor suppressive gene p21, which involves in cell cycle progression." (PMID 32393761, 2020). "Our findings indicate that the chimeric transcript SEPT7P2-PSPH is a product of trans-splicing of two adjacent genes and might be a tumor suppressor gene, potentially having the role of anticancer activity." (PMID 31057610, 2019). "Accumulating studies have reported that the dysregulation of miR-214 is causative for carcinogenesis, which may function as either an oncogene or a tumor suppressor gene dependent on specific types of tumor." (PMID 31058093, 2019). "Our previous study identified CACNA2D3 as a novel tumor suppressor gene for ESCC." (PMID 31001468, 2019). "Furthermore, it was reported UPF1 acts a tumor suppressive gene in HCC, but, the role played by UPF3A, in the pathogenesis of HCC, has not been well studied." (PMID 31856847, 2019). "Evidence has demonstrated that miR-183 plays an essential role in tumorigenesis, which could serve as either an oncogene or a tumor-suppressor gene in different types of cancer." (PMID 31210063, 2019). "Because GOS2 has pro-apoptotic activity and it is epigenetically repressed or down-regulated in human cancers, it could be described as a tumor-suppressor gene." (PMID 31590218, 2019). "NFIB can also act both as an oncogene and a tumor suppressor gene depending on the tumor type." (PMID 31426421, 2019). "It has been reported that ALDH1A2 is a candidate tumor suppressor gene in prostate cancer." (PMID 30944378, 2019). "In a previous research, we demonstrated that EYA4 expression is down-regulated in human HCC tissue and that its suppression is an independent prognostic factor of poor survival, which suggests EYA4 might be a potential tumor suppressor gene in HCC." (PMID 29764501, 2018). "RASAL2, a unique RAS GTPase-activating protein (RAS-GAP), has been reported as a tumor-suppressor gene, which inhibits tumor progression in different types of cancer, such as luminal B breast cancer, ovarian cancer, lung cancer, nasopharyngeal carcinoma, and colorectal cancer." (PMID 30158581, 2018). "However, the idea that the same tumor gene can be classified as an oncogene or a tumor-suppressor gene, depending on the physiologic context, has been previously raised." (PMID 30297765, 2018).
tumor (continued). "In this regard, miR-424 often plays a role as tumor suppressor gene." (PMID 28928430, 2017). "Post irradiation the contrasting expression profiles of PARTICLE and WWOX in such cell lines that represented various WWOX genetic backgrounds suggest a relationship may exist between this lncRNA and this tumor suppressor gene." (PMID 29152092, 2017). "Thus, AHRR has been proposed to function as a putative new tumor suppressor gene in multiple types of human cancers." (PMID 28056099, 2017). "Death-associated protein kinase (DAPK), a tumor suppressor gene, could mediate cell death in INF-γ–induced apoptosis, whereas inactivated DAPK, could lead to the pathogenesis and metastasis of the tumor." (PMID 28249042, 2017). "These GPAT2-induced changes are consistent with its proposed function as a tumor-promoting gene, and might be used as a phenotypic differentiation marker." (PMID 29211789, 2017). "In addition to being able to function as an oncogene, many studies have demonstrated that miR-27a can also play an essential role as a tumor-suppressor gene in the development and progression of various cancer." (PMID 28415619, 2017). "Together, these studies congruously characterized ANGPTL1 as a tumor suppressor gene in cancer." (PMID 28606130, 2017). "Our results revealed that miR-29a-3p is a tumor suppressor gene that acts by directly repressing the oncogene IGF1R, which takes part in immunoregulation in tumor microenvironments in HCC, implying that miR-29a-3p could be a potential target for HCC treatment." (PMID 29156819, 2017). "The E- cadherin is tumor suppression gene that regulates epithelial cell behavior." (PMID 28824426, 2017). "miRNAs may act as a tumor suppressor gene or oncogene, and may regulate tumor invasion and metastasis such as the EMT." (PMID 29262657, 2017). "It has been suggested that the CpG island methylation observed may silence specific tumour-related genes, including the mismatch repair gene MLH1, which may give rise to microsatellite instable tumours." (PMID 27279102, 2016). "Phosphatase and tensin homolog (PTEN) is a tumor-suppressor gene." (PMID 27936183, 2016). "In this study, we demonstrated that miR-218-5p was downregulated in NSCLC tissues and could suppress cell proliferation and migration in vitro and retard tumor growth in vivo, which suggests a role for miR-218-5p as a tumor suppressor gene in NSCLC." (PMID 27057632, 2016). "PTEN is deemed as a tumor suppressor gene that negatively regulates PI3K/Akt signaling." (PMID 27713121, 2016). "P21 is a well-recognized cell cycle inhibitor and a tumor suppressor gene." (PMID 27905892, 2016). "Mounting evidence has demonstrated that miR-506 is a tumor suppressor gene." (PMID 27542202, 2016). "Our results demonstrate that miR-203 serves as a tumor suppressor gene and may be useful as a new potential therapeutic target in CRC." (PMID 27376958, 2016). "Indeed, it has been observed that WT1 can act as a tumor suppressor gene or, in some cases, as oncogene by considering the tumor histotype." (PMID 27014421, 2016). "In our study, KLF4 and IRF8 were up-regulated TFs, and IRF8 was a tumor suppressor gene." (PMID 27405725, 2016). "Smad4 is a tumor-suppressor gene with a key role in the TGF-β signaling pathway." (PMID 25890228, 2015). "It was proposed that the IGFBP-3 gene could be a putative tumor suppressor gene and/or therapeutic target for human cancers." (PMID 26370590, 2015). "DLEU2 is thought to be a tumor-suppressor gene as it is frequently deleted in malignant tumours." (PMID 25822729, 2015). "Their results supported the idea that CSMD1 was a tumor suppressor gene." (PMID 26076954, 2015). "Collectively, our findings indicated that Sesn2 may act as a tumor suppressor gene that can inhibit cancer cell proliferation viability through the regulation of Akt-mTOR-p70S6K signal pathway." (PMID 25962159, 2015).